ENSG00000173366 (novel twinfilin, actin-binding protein, homolog 2 (Drosophila) (TWF2) and toll-like receptor 9 (TLR9) protein)
Gene: Protein-coding gene on chromosome 3 (52,221,081 to 52,231,190, reverse strand). Ensembl gene ENSG00000173366.
Genetic constraint (gnomAD): Loss-of-function variants: 30 observed, 45.52 expected, observed/expected ratio (o/e) 0.66, 90% interval 0.49 to 0.89. Missense variants: 1,263 observed, 1,586.3 expected, observed/expected ratio (o/e) 0.8, 90% interval 0.76 to 0.83. Synonymous variants: 651 observed, 698.54 expected, observed/expected ratio (o/e) 0.93, 90% interval 0.87 to 0.99.